PCSK9 (proprotein convertase subtilisin/kexin type 9)
Diseases named in the same sentence as PCSK9 in open-access papers (continued):
Sharing a sentence is not in itself a finding about the gene and the disease.
cancer (continued). "However, extrahepatic functions of PCSK9 are increasingly studied in the last three years, involving cardiomyocyte, endotheliocyte, macrophage, and cancer cell metabolism, shedding light on possible therapeutic uses of PCSK9 inhibitors to new off-label clinical applications in cardio-oncology." (PMID 36900189, 2023). "This analysis also implies that Pep2-8 may inhibit cell death and apoptosis in tumor/cancer cells, indicating that PCSK9 inhibition may provide benefit to vascular aging but potentially predisposing to neoplasms, a possibility that will require careful evaluation." (PMID 37284459, 2023). "Additionally, our results showed a significant correlation between PCSK9 expression with PDCD1 and CTLA4, which referred to T cell exhaustion and led to the loss of T cell function in patients with common chronic infections and cancer." (PMID 37860186, 2023). "Interestingly, PCSK9 inhibition is being explored as a new cancer therapy to increase the response of tumors to checkpoint therapies, which might be also applied to the treatment of aggressive ECs overexpressing PSCK9." (PMID 36745330, 2023). "Additionally, Liu and colleagues inoculated Pcsk9 knockout mouse cancer cells into syngeneic mouse hosts and observed delayed tumour growth, as well as a synergistic effect between PCSK9 inhibition and anti-PD1 antibody treatment to promote the efficacy of tumour growth suppression." (PMID 36595504, 2023). "Other cholesterol-lowering drugs, such as proprotein convertase subtilisin/kexin type 9 (PCSK9) inhibitors, seem to potentiate immune checkpoint therapy in cancer patients and might even be used as a potential future therapeutic target in personalized cancer medicine." (PMID 37370705, 2023). "Finally, PCSK9 may indirectly influence cancer growth via its cholesterol-regulating function, as the low-density-lipoprotein cholesterol supports tumor development." (PMID 36701413, 2023). "Finally, we believe that inhibiting PCSK9 may be an effective strategy for improving cancer immunotherapy." (PMID 38864086, 2023). "Therefore, PCSK9 expression may be a valuable biomarker for the clinical prognosis of some malignant tumors, including liver, stomach, kidney, pancreatic, and breast cancers." (PMID 36230934, 2022). "Interestingly, PCSK9 influences immune checkpoint regulation in cancer." (PMID 35806470, 2022). "Given this same hypothesis, PCSK9 MABs have also demonstrated reduction in cancer risks." (PMID 36158986, 2022). "Therefore, scientists speculate that PCSK9 may in the future become a valuable biomarker of cancer development." (PMID 35323699, 2022). "Therefore, inhibiting PCSK9 might promote the trafficking of ENaC, while ENaCs are critically engaged in cancer cell biology, such as proliferation, migration, invasion, and apoptosis." (PMID 34712689, 2021). "Since we observed that targeting cholesterol-modulating PCSK9 enzyme with its specific PF-06446846 inhibitor could impair OC cancer cell survival, we decided to investigate the cytotoxic effect of other compounds involved in lipid-metabolism in OC cell lines and PDCs." (PMID 34359627, 2021). "However, little is known about the function of PCSK9-Ab in cancer." (PMID 34504788, 2021). "Furthermore, we found that MAPK signaling pathway was involved in the PCSK9-induced cancer promotion and that the silencing of PCSK9 impeded the phosphorylation of p38 MAPK, ERK1/2, and JNK, thus significantly downregulating the migration and invasion of cells." (PMID 33489919, 2020). "Furthermore, recent studies suggest that PCSK9 may serve as a target for cancer immunotherapy." (PMID 40328788, 2025).
cancer (continued). "Eliminating the effect of PCSK9, whether via direct inhibition or gene knock-out, was shown to attenuate tumor growth in mice cancer cells by decreasing the barriers or checkpoints to T call signaling, which then boosts the anti-tumor immune response to cancer cells." (PMID 38672532, 2024). "The multifunctional TDN-FA/PL1/Pcsk9-siRNA demonstrates efficacy and safety in CRC, thereby broadening the utilization of DNA nanotechnology for novel treatments across different cancer types." (PMID 39324018, 2024). "Our study revealed the correlations between PCSK9 expression and the clinical characteristics and prognosis, TME status, and MHC expression in pan-cancer patients." (PMID 38600469, 2024). "Proprotein convertase subtilisin/kexin type 9 (PCSK9) is a key orchestrator of atherosclerotic process and it is also involved in cancer progression and immune-resistance." (PMID 36900189, 2023). "Thus, aberrant DNA methylation may be responsible for PCSK9 expression in many cancer types." (PMID 37860186, 2023). "PCSK9 genetic deletion or using PCSK9 antibodies enhanced the major histocompatibility protein class I expression on the tumor cell surface, enabling CD8 T cells to identify cancer cells and improving the cytotoxic T cells’ intratumoral infiltration." (PMID 37103355, 2023). "The systemic impacts of PCSK9 on the immune system observed here support the ongoing efforts to target PCSK9 alone and/or in combination with ICB in cancer therapy." (PMID 36588164, 2023). "Little is known on the role, if any, of circulating lipid-related factors such as PCSK9, ANGPTL3 and lipoprotein (a) in cancers." (PMID 36203122, 2022). "Moreover, PCSK9 has a survival role for OC cells, indicating that this proprotein convertase could directly or indirectly modulate tumorigenesis and should be further investigated in cancer therapy." (PMID 34359627, 2021). "Considering the exacerbated glucose uptake property of cancer cells, high glucose availability was maintained by culturing HCC cells in HG medium and expression of PCSK9 was compared with cells cultured in LG medium." (PMID 30386595, 2018). "Next, we treated the HepG2 human cancer cell line with C75 and found that FASN expression and the expression levels of liver‐specific genes, including PKLR, PNPLA3, and PCSK9, were significantly decreased after 24 h." (PMID 28827398, 2017). "Our findings underscored the critical role of PCSK9 in regulating E-cadherin degradation and suggest that PCSK9 could serve as a novel therapeutic target for ATC, with implications for expanding the therapeutic landscape for this aggressive cancer." (PMID 40328788, 2025). "In this observational study, lipid profiles, PCSK9, ANGPTL3, and Lp(a) levels did not change in men diagnosed with locally advanced Gleason 8 or 9 PCa compared to at‐risk but cancer‐free men." (PMID 39888285, 2025). "This study evaluated the safety, tolerability, pharmacokinetics, and initial efficacy of JS002 (Ongericimab), a bioengineered humanized anti-PCSK9 monoclonal antibody, combined with JS001 (Toripalimab), a PD-1 inhibitor, in individuals with progressive cancer for whom standard therapy has failed." (PMID 39324018, 2024).
cancer (continued). "Inhibition of PCSK9 activity with therapeutic antibodies or small interfering RNAs is used in the clinic to lower blood cholesterol, and RNA interference -based silencing of FURIN (PCSK3) is being evaluated in clinical trials as a cancer treatment." (PMID 39430302, 2024). "Thus, this observational study aimed to test the effectiveness of proprotein convertase subtilisin/kexin type 9 (PCSK9), one of the key regulators of cholesterol levels, as a prognostic biomarker in cancer onset." (PMID 38611089, 2024). "Although our pan-cancer analysis did not include related gender factors, the relationship between the abnormal expression of PCSK9 related to gender and the prognosis, immune infiltration and treatment of tumor deserves further consideration." (PMID 37860186, 2023). "PCSK9 expression levels significantly correlated with immune cells (CD8+ T cells in 14 types of cancer, dendritic cells (DCs) in 11 types of cancer, and macrophages in 13 types of cancer)." (PMID 37860186, 2023). "Furthermore, we investigated the relationship between the PCSK9 CNV and immune infiltration in various cancers." (PMID 37860186, 2023). "To further unravel the potential predictive value of PCSK9 gene alterations for ICI treatment, we then investigated the relationship between PCSK9 alterations and six common immune infiltrates (B cells, CD4+ T cells, CD8+ T cells, macrophages, neutrophils, and DCs) across multiple cancer types." (PMID 37860186, 2023). "If future studies reveal that PCSK9, ANGPTL3 or Lp(a) have a role to play in cancer progression, the availability of inhibitors -for which safety data are available in humans- could permit to reposition these inhibitors in cancers." (PMID 36203122, 2022). "We propose that either the rise of PCSK9 levels in our study was too small to lead to a significant increase in LDL-C levels, or that it did lead to a transient rise in LDL-C levels that was compensated by the uptake of LDL-C by cancer cells." (PMID 36203122, 2022). "To date, however, there are no clinical trials that describe the effect of the use of PCSK-9 inhibitors used in lipid-lowering therapy on the development and progression of neoplasms in cancer patients." (PMID 33808697, 2021). "As there was not confounding in these factors, and there was no report for serum PCSK9 antibody and cancer, we considered as follows." (PMID 34504788, 2021). "In the context of cancer, however, there are no strong data supporting the concept that PCSK9 in general affects cancer incidence." (PMID 33364976, 2020). "As such, the absence of changes in Lp(a), PCSK9 and ANGPTL3 levels between men with localized PCa and men at risk could depend on the investigated cancer stage." (PMID 39888285, 2025). "Importantly, the pro-metastatic effects of PCSK9 were found to be independent of its canonical role in cholesterol metabolism, highlighting a novel and distinct function for this protein in cancer biology." (PMID 39872986, 2025). "However, through a literature search, we failed to retrieve any publications with a pan-cancer analysis of PCSK9 from the perspective of overall tumors." (PMID 38600469, 2024). "Therefore, it is conceivable that cancer patients treated with ICIs, particularly those diagnosed with ASCVD, could potentially benefit from PCSK9 therapy." (PMID 38887452, 2024). "Furthermore, the multifaceted functions of PCSK9 in cancer development and the regulation of TIME have not been comprehensively addressed." (PMID 38185721, 2024).
cancer (continued). "Furthermore, combining PCSK9 inhibitors with OVA-II peptide vaccines can achieve better anti-tumor effects, providing evidence for applying PCSK9 inhibition as a promising immunoregulatory therapeutic strategy for cancer treatment." (PMID 38600469, 2024). "The lack of reductions in cancer incidence in clinical trials on cardiovascular conditions by anti-PCSK9 antibodies evolocumab and alirocumab might be attributable to the presence of cancerous lesions at time when the antibodies were administrated." (PMID 36588164, 2023). "To date, no studies have evaluated if PCSK9 blocking agents could reduce ASCVD in cancer patients treated with ICIs." (PMID 36900189, 2023). "Moreover, data confirm that PCSK9 inhibition using alirocumab or evolocumab potentiates immune checkpoint inhibition therapy, specifically anti-PD1 antibody treatment, in mouse models of cancers." (PMID 36986246, 2023). "Third, the combination of PCSK9 inhibitors and Rapamycin could enhance the inhibition of the STAT3 signaling pathway, promote apoptosis, and reduce the potential proliferation and metastatic ability of malignant tumors." (PMID 37896137, 2023). "Indeed, of the eight CRC GWAS loci found within this subset of CRC-related smoking genes, CDCA8, CDKN3, FADS1, FADS2, MYBL2, PCSK9, and PRC1, have all been reported to be overexpressed in others cancers and to play important roles in the DNA damage response pathway." (PMID 37509213, 2023). "While PCSK9 levels increased with cancer stage, cholesterol levels did not follow the same trend." (PMID 36203122, 2022). "The role of non-statin therapies, including ezetimibe, PCSK9 inhibitors, bempedoic acid and icosapent ethyl in the management of lipid disorders in patients with cancer remains largely unknown." (PMID 35548413, 2022). "Similarly, despite an increase in PCSK9 levels between benign disease vs stage III cancers, no changes in LDL-C, non-HDL or Apo B were observed." (PMID 36203122, 2022). "Therefore, PCSK9 plays a central role in the pathogenesis of CVD and cancers." (PMID 34782856, 2021). "Statistically significant borderline differences in PCSK9 levels was observed between females and males (mean 200.7 ± 220.3 vs 302.0 ± 263.1 ng/mL; P = .071), and between patients with or without history of cancer (mean 165.8 ± 188.1 vs 279.3 ± 257.8 ng/mL; P = .078)." (PMID 33969232, 2021). "PCSK9 inhibitors have not been reported to affect cancer incidence in clinical trials." (PMID 35097027, 2021). "But there was no report of relationship between serum PCSK9 antibody and cancer." (PMID 34504788, 2021). "The statistically significant difference in the baseline PCSK9 level was maintained until achieving SVR, leading to a parallel decrease in PCSK9 level in patients taking or not taking statins, between male and female patients, and between patients with or without history of cancer." (PMID 33969232, 2021). "But there was no report concerned to the relationship between serum PCSK9 autoantibody and cancer." (PMID 34504788, 2021). "However, epidemiological data do not support a strong correlation between cancer and PCSK9 in general." (PMID 33364976, 2020).
cancer (continued). "The use of cholesterol-lowering drugs (e.g., statins, PCSK9 inhibitors) may play a role in tumor immunotherapy by promoting the conversion of cold tumors to hot tumors, enhancing CD8+ T cell activity, and reducing PD-L1 expression in cancer cells, thus inhibiting tumor progression." (PMID 41245411, 2025). "However, the function of PCSK9 in human cancers has not been determined, and it is not yet known if PCSK9 could have a significant impact on the immunological crosstalk associated with cancer and, in turn, affect the prognosis of different cancer types." (PMID 37860186, 2023). "However, in a recent study PCSK9 inhibition could potentiate anti-tumor immune responses and thus substantially reduced tumor growth in murine cancer models, which was independent of cholesterol-lowering." (PMID 35097027, 2021). "It indicates that lipid profiles, PCSK9, ANGPTL3, and Lp(a) levels were not significantly altered in localized high‐grade (Gleason 8 or 9) PCa patients compared to cancer‐free men." (PMID 39888285, 2025). "We assess that PCSK9 i represent a promising lipid-lowering strategy in patients with CKM syndrome and cancer; they provide cardiovascular protection, have no renal toxicity, and are generally well tolerated." (PMID 40227756, 2025). "The presence of cancer did not modify Apo CIII and PCSK9 levels (see HGSOC and BOL)." (PMID 38414008, 2024).